DMD (dystrophin)
Diseases named in the same sentence as DMD in open-access papers (continued):
Sharing a sentence is not in itself a finding about the gene and the disease.
myopathy (54 papers, 2010 to 2025). A disease of the muscle in which the muscle fibers do not function properly. "Dystrophic myopathies, such as dystrophin-deficient myopathies, result in polyphasic muscle degeneration and regeneration, variation in myofibre diameter and dystrophic calcification." (PMID 39765607, 2024). "Our this finding is of high interest, as previous studies suggest under-expression of DMD gene to be associated with low levels of dystrophin protein, which leads to myopathy and cell necrosis in ChAc patients." (PMID 39292690, 2024). "Specifically, X-linked cardiomyopathy patients with only 29% of normal dystrophin levels exhibit sub-clinical myopathy." (PMID 36420212, 2022). "In order to assess the abundance of various myopathy-related proteins in the four fiber types, we investigated the expression patterns of dystrophin and several myofibrillar myopathy-associated proteins in more detail." (PMID 34201234, 2021). "Existing zebrafish myopathy models, such as sapje, which carries a mutated dystrophin gene have been used to screen FDA-approved compounds for potential therapeutics." (PMID 29196645, 2017). "Nonetheless, removal of clp-1 substantially suppressed the muscle degeneration associated with C. elegans dys-1; hlh-1(cc561ts) DMD, which is based on a mouse model of myopathy involving the combined mutation of MyoD and dystrophin." (PMID 22479198, 2012). "But it is interesting to note that it is also not fully understood why loss of dystrophin causes a fatal MD in humans while only a mild myopathy in mice." (PMID 21533183, 2011). "The main difficulty in the genetic diagnosis of myopathies is the large number of different types of causative variants, even in the same gene (e.g., deletions or missense variants in the DMD gene), for which a large number of techniques are required for detection and interpretation." (PMID 40883749, 2025). "Indeed, mTOR deficiency leads to reduced muscle dystrophin content and causes dystrophic defects leading to severe myopathy." (PMID 36402791, 2022). "Furthermore, upregulation of Nogo-A in dystrophin-deficient (mdx) murine model, myopathy and Duchenne muscle dystrophy (DMD) clinical biopsies was associated with upregulation of CHOP, IL-6 and TNF-α." (PMID 33572505, 2021). "Desmin and dystrophin-related myopathies are often associated with debilitating dysfunction and myopathy is compounded in desmin and dystrophin double-knockout mice, which manifest a remarkable dystrophic phenotype with profound deterioration of sarcomere organisation and Z-line alignment." (PMID 34067869, 2021). "Since a dystrophic pattern of myopathy was reported in some rare cases, an involvement of dystrophin (whose gene is 4 Mb upstream of XK on the X chromosome) was sought but not confirmed." (PMID 33652783, 2021). "Mutant mice that lack MyoD and dystrophin displayed a significant increase in the severity of myopathy and premature death, highlighting the role of MyoD in muscle regeneration." (PMID 33213081, 2020). "One possibility would be that reduced MUSK and dystrophin expression lead to remodeling of the muscle and adaptations of growth to compensate, but these changes ultimately lead to myopathy." (PMID 30820362, 2019). "Mutations in the DMD gene, encoding for dystrophin, are responsible for X-linked DCM and myopathies." (PMID 28750076, 2017). "The myopathy was more severe in mTOR knockout than in Raptor knockout mice, possibly due to reduction in the content of dystrophin and other components of the dystrophin-glycoprotein complex." (PMID 21798082, 2011). "C. elegans is a model organism used to dissect the molecular mechanism of myopathy associated with mutations in the DGC components dyb-1 and dys-1 (WormBase: WBGene00001131, the orthologue of dystrophin)." (PMID 20498707, 2010).
myopathy (continued). "The deletion of exon 52 of the DMD gene, a mutation frequently present in humans, through a targeted replacement of exon 52 with a neomycin resistance cassette (neo®), led to the generation of DMD∆52 pigs with typical signs of DMD, including mobility impairment and severe myopathy." (PMID 38247849, 2024). "Any modification in the dystrophin complex structure could result in various myopathies amongst which the DMD, which is the most common myopathy." (PMID 35419381, 2022). "Interestingly, epicatechin has been shown to restore the expression of dystrophin and other key cytoskeletal proteins in models of myopathy such as Becker muscular dystrophy and diabetes." (PMID 34298829, 2021). "Both muscles suffered severe myopathy, indicated by loss of dystrophin positive immunostaining and the absence of stimulation induced isometric force production at HLI d14." (PMID 31316393, 2019). "Even though the molecular mechanisms causing the DMD CM death are somewhat described, no sufficient explanation on delayed myopathy development leading to muscle wasting has been offered." (PMID 30650618, 2019). "Muscular type I fiber predominance is likewise a common finding in dystrophin myopathies." (PMID 26881790, 2016). "This progressive myopathy does not appear to be due to loss of microdystrophin in the mice over time, as we initially anticipated, but rather is caused by the failure of microdystrophin to rescue all functions of full-length dystrophin, as in BMD." (PMID 38713520, 2024). "Importantly, loss of dystrophin and reduction of fast MHC resulted in reduced twitch tension (−35 ± 7% at 100 Hz tetanus, n = 8, P < 0.05) and prolonged contraction and relaxation times demonstrating that ESM culture unmasks early changes of DMD myopathy." (PMID 36254806, 2022). "Taken together, the detected loss of important dystrophin complex components in the heart of the DMD animals indicates that both functions associated with this complex, signal transduction, and cell membrane stabilization may be impaired and may cause a severe myopathy." (PMID 32927262, 2020). "GRMD dogs, a large animal model of DMD, develop the progressive myopathy on both clinical and histological aspects owing to the absence of dystrophin." (PMID 32157826, 2020). "In addition, investigations should be carried out on more hereditary myopathies candidate genes, including α-B crystalline (CRYAB), dystrophin (DMD) and myotilin (MYOT) in the future." (PMID 24948216, 2014).
cardiac disease (14 papers, 2011 to 2025). "Identifying the genetic background, in addition to DMD disease-causing variants, is one of the unmet needs in understanding the cardiac disease’s pathogenetic mechanisms and its prognostic implications." (PMID 39857686, 2025). "We identified four observational studies reporting evidence of effects of DMD mutations on cardiac disease in DMD." (PMID 39342355, 2024). "We further investigated the association of dystrophin with cavins and caveolae since caveolae-associated proteins, including cavin-1, cavin-4 and caveolin-3 have been implicated in cardiac disease." (PMID 33949649, 2021). "Women carriers heterozygous for DMD gene mutations are also at an increased risk for clinical heart disease due to mosaic cardiac dystrophin expression." (PMID 35252412, 2021). "The detailed molecular pathomechanism leading to cardiac disease in MD patients is still to be elucidated, although the underlying genetic dystrophin defect can be identified easily by appropriate mutation screening." (PMID 27150296, 2016). "The exact molecular mechanisms underlying dystrophin-deficient heart disease remain to be fully clarified." (PMID 21834967, 2011). "Results would be highly informative not only for micro-dystrophin gene therapy but to understand risk factors that may trigger cardiac disease in BMD patients expressing internally deleted dystrophins with impaired associations with cavins." (PMID 33949649, 2021). "Our results suggest that AAV SERCA2a therapy may hold great promise in treating dystrophin-deficient heart disease." (PMID 21834967, 2011). "According to different studies reported in the literature, variant localization may reflect some specific cardiovascular characteristics such as the onset of DCM related to pathogenic variants in DMD exons 12 and 14–17 or the presence of heart diseases in patients carrying variants in exons 31–42." (PMID 39857686, 2025). "Overall, our findings suggest new avenues of research into the role of dystrophin in cardiac remodeling in general and more specifically into the molecular underpinnings of cardiac disease in DMD and BMD patients." (PMID 33949649, 2021). "Importantly, we identified novel cardiac-specific interactions of dystrophin with proteins known to regulate cardiac contraction and to be involved in cardiac disease." (PMID 22937058, 2012). "While [18F]FDG can be used as an analogue of inflammation in several neurological and cardiac diseases, it should be noted that these specific studies were focused on investigating the metabolic functionality of dystrophin-deficient tissue regions rather than its associated peripheral inflammation." (PMID 37108685, 2023). "In this study, we have compared the cardiac protein complexes assembled by dystrophin and μDys with the primary goal of identifying protein associations not fully rescued by μDys that might be relevant to cardiac disease/physiology." (PMID 33949649, 2021). "A direct regulation of ERK by dystrophin implies that ERK signaling is impaired early in the DMD heart and is likely an important contributor to cardiac disease progression in DMD." (PMID 33949649, 2021). "These 3 antibodies uniformly detected the expression of dystrophin in the LV heart tissue of a patient with no history of cardiac disease." (PMID 37426526, 2023).
infection (10 papers, 2008 to 2025). The state of being infected such as from the introduction of a foreign agent such as serum, vaccine, antigenic substance or organism. "This persistent infection was characterized by molecular detection of only 5′TD RNA forms that were associated with dystrophin cleavage in the heart and insulin production impairment in beta-pancreatic cells." (PMID 36016091, 2022). "ACTA1, typically associated with skeletal muscle actin, and SGCG (Sarcoglycan Gamma), a component of the dystrophin–glycoprotein complex, are often linked to muscle integrity and may indicate cytoskeletal or structural alterations in the kidney post-infection." (PMID 40863220, 2025). "We observed an average of 55% GFP‐positive fibers within the dystrophin border, indicating successful infection with the lentivirus in the muscle fibers." (PMID 39761956, 2025). "In cardiac cells, the CVB-TD RNA population’s infection induced the disruption of dystrophin by sufficiently maintained viral proteinase-induced cleavage activities." (PMID 36560784, 2022). "In P. monodon, miR-4286 and miR-107b were significantly changed after VPAHPND infection which might regulate dystrophin expression, calcium concentration upon infection." (PMID 33589707, 2021). "Importantly, infection of both target cell types with the control vector dHV.F50 alone or together with hcAd.FLPe.F50 gave rise to similar STFs as observed for HeLa cells and DMD myoblasts transduced exclusively with dHV.68/5′3′.F50." (PMID 18769728, 2008).
muscular disorder (9 papers, 2012 to 2025). "DMD remains an incurable muscular disorder, and the proposed replacement of the dystrophin gene is associated with multiple technical problems and only few and limited positive results." (PMID 30279586, 2018). "For patients with CPK elevation, further investigation regarding the cause of a muscular disorder other than that for DMD/BMD and Pompe disease was not performed." (PMID 37818166, 2023). "DMD is the most common muscular disorder caused by mutations in the dystrophin gene and results in absent or insufficient functional dystrophin, which leads to reduced sarcolemma stability and rendering the muscle fibers vulnerable to mechanical stretching-induced injury." (PMID 33286487, 2020). "Cellular uptake, nuclear transport, and subsequent DMD gene editing were observed in this study, suggesting a stable and safe nonviral strategy for gene therapy in muscular disorders." (PMID 39949979, 2025).
neurodevelopmental disorder (9 papers, 2017 to 2025). A behavioral and cognitive disorder with onset during the developmental period that involves impaired or aberrant development of intellectual, motor, or social functions. "This is of particular interest regarding the cerebral dystrophin isoforms, which play a crucial role in the development and function of the human brain and are coexpressed with genes implicated in neurodevelopmental disorders." (PMID 33096920, 2020). "Lack of dystrophin and its mutations disrupt brain isoforms and are more likely to be associated with neurodevelopmental disorders." (PMID 36315559, 2022). "In summary, studies suggest that dystrophin might play a critical role in brain development and potentially in the neurobiology of neurodevelopmental disorders." (PMID 34640386, 2021). "To get more insight into the functional role of dystrophin throughout human brain development and its association to other neurodevelopmental disorders, we analysed the spatial and temporal expression pattern relationships of the DMD gene and the different dystrophin isoforms." (PMID 28974727, 2017). "However, the full role of dystrophin isoforms in the brain remains largely unclear; it is only recognized that the brain is affected by the lack of dystrophin and notably that mutations disrupting the brain isoforms Dp140 and Dp71 are more frequently associated with neurodevelopmental disorders." (PMID 34640386, 2021). "Therefore, further studies are required to analyze this association in depth and ultimately to understand the role of the brain dystrophin isoform in the pathogenesis of ASD and other neurodevelopmental disorders." (PMID 34640386, 2021).
genetic muscle disorder (7 papers, 2014 to 2025). "DMD is a rare genetic muscle disorder caused by mutations in the dystrophin gene, leading to the absence of the dystrophin protein." (PMID 39609384, 2024).
cardiovascular disease (5 papers, 2017 to 2022). "Dystrophin is a large protein in which mutations can result in progressive muscle weakness, respiratory distress, and cardiovascular disorder." (PMID 35620579, 2022). "Mutations of the following genes can lead to cardiovascular disease: Filamin A, EMD (emerin), LAMP2 (lysosomal-associated membrane protein 2), DMD (dystrophin), TAZ (tafazzin), and VEGF-D (vascular endothelial growth factor D)." (PMID 30459711, 2018).
metabolic disease (3 papers, 2014 to 2021). A congenital disorder (due to inherited enzyme abnormality) or acquired (due to failure of a metabolically important organ) disorder resulting from an abnormal metabolic process. "Interestingly, early observations prior to the discovery of the DMD gene had hypothesized that DMD was a mitochondrial/metabolic disease based on protein quantifications and enzyme activities." (PMID 33586340, 2021). "Despite that MLPA is now the most widely used technique for identifying duplication in DMD, targeted exome sequencing is prefered when evidence for a diagnosis of DMD is insufficient and when other metabolic diseases have not been ruled out." (PMID 28344651, 2017).
nervous system tumors (3 papers, 2021 to 2025). "A complex picture of DMD, and likely DAPC, disruption within nervous system tumours is apparent since alterations in the dystrophin-associated protein α-dystroglycan have also been reported in human gliomas." (PMID 33188621, 2021).
degenerative disease (2 papers, 2007 to 2023). "However, in C. elegans, as in mouse, mild MyoD (hlh-1) mutations in conjunction with dystrophin deficiencies act synergistically to induce muscle disassembly; this finding suggests that C. elegans may be a useful model for studying these degenerative diseases." (PMID 17848203, 2007).
skeletal dysplasia (2 papers, 2021 to 2023). Any Mendelian diseases that affects growth and development of the skeleton. "In this study, the genetic cause of 16 Chinese fetuses with skeletal dysplasia were analyzed, and 12 cases yielded positive results including one deletion in DMD gene detected by SNP-array and 14 variants in other 6 genes detected by whole exome sequencing (WES)." (PMID 33777089, 2021).
bacterial infections (1 paper, 2024). "Another target, Nr1h3 (or Lxrα), which plays a crucial role in the macrophage response to intracellular bacterial infections, inflammatory response, and metabolic homeostasis, showed the same pattern of expression, as observed in DMD samples." (PMID 38339055, 2024).
musculoskeletal diseases (1 paper, 2023). "We have conducted exome sequencing for DMD multiplex PCR negative participants to identify novel mutations and genes related to musculoskeletal diseases." (PMID 38057384, 2023).
DMD also shares sentences with these, for which no sentence is quoted: -deficient (8 papers); Marfan syndrome (5); congenital myopathy (4); gastrointestinal stromal tumor (4); neurological disease (4); schizophrenia (4); hemophilia B (3); mucopolysaccharidosis (3); osteoporosis (3); X-linked myotubular myopathy (3); Adrenal insufficiency (2); Alzheimer disease (2); arrhythmogenic right ventricular cardiomyopathy (2); attention deficit-hyperactivity disorder (2); Bethlem myopathy (2); bladder urothelial cancer (2); cerebellar disorder (2); congenital muscular dystrophies (2); cytomegalovirus retinitis (2); dilatation (2); facioscapulohumeral muscular dystrophy (2); familial hypercholesterolemia (2); hearing loss (2); hematologic malignancies (2); Long QT syndrome (2); neurofibromatosis (2); neuronal ceroid lipofuscinosis (2); Noonan syndrome (2); obsessive-compulsive disorder (2); osteosarcoma (2).
A further 159 diseases each share a sentence with DMD in 2 papers or fewer.